PRODH (proline dehydrogenase 1)
Description:
Converts proline to delta-1-pyrroline-5-carboxylate.
Synonyms: PIG6; PRODH2; HSPOX2; PRODH1; TP53I6; POX
Tractability: PROTAC: ubiquitination databases record sites on it.
Gene: Protein-coding gene on chromosome 22 (18,912,774 to 18,936,553, reverse strand). Ensembl gene ENSG00000100033.
Subcellular location: Mitochondrion matrix
Subcellular location (Human Protein Atlas): Mitochondria; Nucleoplasm; Vesicles
Pathways (Reactome):
Metabolism: Proline catabolism
Gene Ontology:
Molecular function: FAD binding; oxidoreductase activity, acting on the CH-NH group of donors, quinone or similar compound as acceptor; proline dehydrogenase activity
Biological process: regulation of oxidative stress-induced neuron intrinsic apoptotic signaling pathway; intrinsic apoptotic signaling pathway in response to oxidative stress; L-proline catabolic process; trans-4-hydroxy-L-proline catabolic process
Cellular component: mitochondrion; mitochondrial inner membrane; mitochondrial matrix
Gene-disease validity (ClinGen):
ClinGen rates the evidence that PRODH causes each of these diseases.
hyperprolinemia type 1 (autosomal recessive): Definitive. Hyperprolinaemia type I is an inborn error of proline metabolism characterized by elevated levels of proline in the plasma and urine.
Homologues: Orthologues: mouse Prodh (82% identical), rat Prodh (81% identical), tropical clawed frog prodh (67% identical), zebrafish prodha (64% identical), Drosophila melanogaster slgA (48% identical), chimpanzee PRODH (44% identical), Caenorhabditis elegans prdh-1 (44% identical), zebrafish prodhb (42% identical). Paralogues in human: PRODH2 (30% identical).
Diseases named in the same sentence as PRODH in open-access papers:
PRODH is named in the same sentence as 98 diseases in open-access papers, as found by Europe PMC text mining. Sharing a sentence is not in itself a finding about the gene and the disease. The quoted sentences say what the papers report.
breast cancer (42 papers, 2015 to 2025). A primary or metastatic malignant neoplasm involving the breast. "This underlines the reasoning behind the recent focus on PRODH-targeted therapy using inhibitors in oncology, demonstrating the treatment efficacy of this strategy in both lung and breast cancer." (PMID 38612551, 2024). "In contrast, proline catabolism via PRODH was shown to support spheroidal breast cancer growth via ATP production and was also found to be increased in lung metastases compared to primary breast cancer tumours using 13C6-glucose as a tracer." (PMID 39816516, 2025). "A stronger inhibitory potential of N-PPG compared to the other inhibitors has also been reported for the ProDH of a human breast cancer cell line." (PMID 41296118, 2025). "In breast cancer, PRODH promotes apoptosis in breast cancer cells and is correlated with a better prognosis." (PMID 39457440, 2024). "Another group’s study has shown that PRODH mRNA levels positively correlate with the outcomes in breast cancer." (PMID 39457440, 2024). "On the other hand, in the MCF7 breast cancer cell line, PRODH downregulation was shown to promote autophagy, whereas its upregulation would promote apoptosis." (PMID 38255788, 2024). "In this study, we have identified the key role of PRODH in tamoxifen response via regulating ferroptosis in breast cancer." (PMID 39457440, 2024). "More recently, however, PRODH expression was shown to sustain invasion and metastatization in breast cancer cells and to promote pancreatic tumor growth." (PMID 38255788, 2024). "Data from clinical specimens demonstrates a significantly higher expression of PRODH in metastases compared to primary breast cancer tumors." (PMID 38023181, 2023). "In particular, compared with primary breast cancer in patients and mice, the expression of PRODH and proline catabolism in metastatic tumors were increased." (PMID 36998464, 2023). "For instance, in breast cancer, high expression of PRODH promotes the apoptosis of cancer cells, but it also contributes to the formation of lung metastases." (PMID 38023181, 2023). "To confirm the role of PRODH/POX in the mechanism of NSAID-induced apoptosis we obtained an MCF7 CRISPR/Cas9 PRODH/POX knockout breast cancer cell model (MCF7POK-KO)." (PMID 35409177, 2022). "Pro catabolism is reported in in vivo metastasis formation through high expression of proline dehydrogenase (PRODH) compared to primary breast cancers of patients and mice." (PMID 35046467, 2022). "The aim of the study was to establish the role of PRODH/POX in NSAID-induced apoptosis in breast cancer cells." (PMID 35409177, 2022). "Here, we present the results on an alternative COX2-independent mechanism of NSAID-induced apoptosis: the PRODH/POX stimulators in breast cancer MCF7 cells." (PMID 35163433, 2022). "The POX/PRODH expression level was correlated with better prognoses in estrogen receptor-positive (ER+) breast cancer patients and with apoptosis induction in MCF-7 cells." (PMID 35454935, 2022). "These processes are potentially involved in the mechanism of PRODH/POX-independent apoptosis in breast cancer cells." (PMID 35409177, 2022). "In this report, we considered the NSAIDs to be agonists of PPARγ-induced PRODH/POX-dependent apoptosis in breast cancer MCF7 cells." (PMID 35163433, 2022). "The data suggest that targeting proline metabolism and the PRODH/POX–PPARγ axis can be considered a novel approach for breast cancer treatment." (PMID 35163433, 2022). "This suggests that targeting proline metabolism and the PRODH/POX–PPARγ axis can be considered a novel approach for breast cancer treatment." (PMID 35163433, 2022). "We have found that NSAIDs, as PPARγ agonists, activate PRODH/POX-induced ROS-dependent apoptosis in breast cancer MCF7 cells." (PMID 35163433, 2022).
breast cancer (continued). "On the other hand, proline degradation by proline dehydrogenase (PRODH) sustains breast cancer metastases and promotes epithelial to mesenchymal transition in lung cancer, effects sensitive to PRODH inhibitor L-tetrahydro-2-furoic acid (L-THFA)." (PMID 36582801, 2022). "Proline is another example of an amino acid that has been postulated to be important for metastasis formation, as its catabolism through PRODH supports proliferation in the 3D culture of breast cancer cells." (PMID 33915900, 2021). "It suggests that PRODH/POX is involved in ROS production in PRODH/POX expressing breast cancer cells." (PMID 34682765, 2021). "PRODH/POX-induced apoptosis (through ROS generation) in breast cancer cells is dependent on proline availability." (PMID 34682765, 2021). "Proline catabolism via proline dehydrogenase (PRODH) also enhances growth of breast cancer cells in 3D culture conditions." (PMID 33401771, 2021). "Nevertheless, based on the cited facts, it seems that blocking the function of both estrogen receptors promotes PRODH/POX-dependent apoptosis in breast cancer cells." (PMID 34943229, 2021). "In fact, PRODH knockdown impairs the capacity of breast cancer cells to form spheroids in vitro and lung metastases in vivo." (PMID 33401771, 2021). "Along with collagen degradation, the proline-consuming enzyme PRODH, also known as proline oxidase, has been shown to be upregulated in breast cancer-derived metastasis." (PMID 34291343, 2021). "Taken together, stimulation of PRODH/POX by celecoxib contributes to inhibition of breast cancer cell growth through activation of PRODH/POX-dependent apoptotic pathways." (PMID 34577574, 2021). "Metformin treatment of MCF-7 breast cancer cells or PRODH/POX-knock out of the cells induces apoptosis by reprograming of amino acid metabolism, TCA, Urea cycle and pentose phosphate pathway in the cells." (PMID 34944532, 2021). "The data presented in this report suggest that TGZ-induced PRODH/POX-dependent apoptosis is conditioned by the status of the ERs in breast cancer cells." (PMID 34682765, 2021). "It suggests that MET treatment or PRODH/POX-knock out induce similar metabolic effects (glucose starvation) and glycolysis is tightly linked to glutamine metabolism in MCF-7 breast cancer cells." (PMID 34944532, 2021). "The data suggest that induction of PRODH/POX by Cx correlates with the increase in the indicated parameters of energetic metabolism in breast cancer cells." (PMID 34577574, 2021). "The data for the first time suggest that celecoxib induces apoptosis through upregulation of PRODH/POX in MCF-7 breast cancer cells." (PMID 34577574, 2021). "Accordingly, studies suggest that proline metabolism, through proline dehydrogenase (PRODH) and proline dehydrogenase reductase (PYCR), is associated with breast cancer metastasis, being upregulated in metastases compared to primary breast cancer tumors." (PMID 34150624, 2021). "It has been considered that estrogens determine efficiency of troglitazone (TGZ)-induced PRODH/POX-dependent apoptosis in breast cancer cells." (PMID 34682765, 2021). "Estrogens and anti-estrogenic compounds have been shown to influence breast cancer cell survival/apoptosis via action through the mitochondrial enzyme proline dehydrogenase/proline oxidase (PRODH/POX)." (PMID 34943229, 2021). "In fact, it has been previously suggested that collagen biosynthesis is stimulated by ERβ while inhibition of collagen biosynthesis induces PRODH/POX-dependent apoptosis in breast cancer cells." (PMID 34682765, 2021). "This study investigated the role of estrogen receptor activation on troglitazone (TGZ)-induced PRODH/POX -dependent apoptosis in four models of breast cancer cells." (PMID 34682765, 2021). "Together with its role in metastatic spread in breast cancer, PRODH has been shown to instigate EMT reprogramming and to increase migration and invasion of NSCLC cells." (PMID 33083024, 2020).
breast cancer (continued). "Human metastatic breast cancer tissue has also been shown to contain higher levels of PRODH/POX and proline catabolism when compared to the primary breast tumor tissue, suggesting that proline metabolism has a role in metastasis." (PMID 33172086, 2020). "It has been reported that proline dehydrogenase (PRODH) mediated proline catabolism is required for breast cancer cells grown in 3D culture." (PMID 30691108, 2019). "There was an increase in PRODH expression in metastatic compared to primary tumors in breast cancer patients as well as in a 4T1 mouse model." (PMID 30691108, 2019). "One of the best characterized breast cancer cells in respect to collagen biosynthesis, prolidase activity and PRODH/POX expression is MCF-7 cell line." (PMID 29568391, 2018). "We found that in all tested breast cancer cell lines PRODH expression increased during spheroidal growth." (PMID 28492237, 2017). "In particular, we find that PRODH expression and proline catabolism is increased in metastases compared to primary breast cancers of patients and mice." (PMID 28492237, 2017). "Consistently, we found that MYC expression is inversely correlated with PRODH expression in primary breast cancer tissue compared to metastases tissue of patients." (PMID 28492237, 2017). "We measured the expression of PRODH in cell lines isolated from human or murine breast cancers (MCF7, HCC70, MDA-MB-231 and 4T1) during spheroidal (3D) compared to attached (2D) growth." (PMID 28492237, 2017). "To investigate whether ferroptosis mediates the role of PRODH in tamoxifen response in breast cancer cells, we treated tamoxifen-resistant cells with a ferroptosis inhibitor fer-1." (PMID 39457440, 2024). "Recent studies suggest the key role of PRODH in breast cancer." (PMID 39457440, 2024). "PRODH sensitizes breast cancer to tamoxifen through ferroptosis." (PMID 39457440, 2024). "In patients with low PRODH expression, ferroptosis activator reagents may provide a potential strategy when combined with tamoxifen to treat this type of breast cancer." (PMID 39457440, 2024). "More importantly, we found that ferroptosis induced by PRODH could potentially overcome tamoxifen resistance in the treatment of breast cancer." (PMID 39457440, 2024). "It was reported that PRODH, the key enzyme for proline degradation, could support growth of breast cancer cells in 3D culture, and promote the formation of lung metastasis in mice models." (PMID 36998464, 2023). "It has been reported that proline catabolism driven by PRODH promotes metastasis of breast cancer." (PMID 38023181, 2023). "For example, in metastatic breast cancer increased proline catabolism is observed via proline dehydrogenase (PRODH) upregulation compared to primary breast cancer cases, Similarly asparagine is known to increase the metastatic and invasive capabilities in breast cancer cells." (PMID 36811317, 2023). "Strikingly, the formation of breast cancer-derived lung metastases in vivo was reduced by using L-THFA to inhibit PRODH activity, indicating that PRODH could be a potential target for inhibiting breast cancer metastasis formation." (PMID 38023181, 2023). "PRODH expression has been reported to be related to apoptosis in patients with breast cancer." (PMID 36180848, 2022). "The possible mechanism for inhibition of the PI3K/AKT pathway and enhancement of breast cancer cell apoptosis by ER modulators (e.g., equol, biochanin A, daidzein) could be related to PRODH/POX-dependent ROS generation." (PMID 34943229, 2021). "Moreover, PRODH expression and proline catabolism are increased in metastatic tumors compared to primary breast cancers of patients and mice." (PMID 33401771, 2021). "The data suggest that PRODH/POX-induced apoptosis is dependent on ER status in breast cancer cells." (PMID 34943229, 2021).
breast cancer (continued). "In addition, the use of the PRODH inhibitor L-THFA is sufficient to impair formation of lung metastases in orthotopic mouse models, indicating that PRODH is a potential drug target for metastasis inhibition in breast cancer patients." (PMID 33401771, 2021). "We propose a hypothesis that PRODH/POX serves as a molecular effector for celecoxib-induced apoptosis in MCF-7 breast cancer cells." (PMID 34577574, 2021). "It has been considered that ER status of breast cancer cells and estrogen availability might determine proline dehydrogenase/proline oxidase (PRODH/POX)-dependent apoptosis." (PMID 34943229, 2021). "It suggests that ERβ may participate in the inhibition of PRODH/POX-dependent ROS generation in breast cancer cells." (PMID 34682765, 2021). "Proline catabolism by PRODH also supports metastasis of breast cancers to the lung." (PMID 33915900, 2021). "It is known that PRODH/POX contributes to autophagic phenotype in breast cancer cells." (PMID 34577574, 2021). "Having demonstrated that Cx blocks cell cycle progression in MCF-7 breast cancer cells, we further investigated whether PRODH/POX affected the cell cycle." (PMID 34577574, 2021). "Thus, it appears that PYCR1 and ProDH/Pox are attractive targets in Pro-starvation therapies of some tumor types such as ccRCC, breast cancer, and HCC." (PMID 33477430, 2021). "Moreover, PRODH is upregulated in a 3D spheroidal cell culture model of breast cancer (BC) compared to the 2D culture, as well as in metastases compared to primary tumors in BC patients." (PMID 32500033, 2020). "Moreover, PRODH overexpression was observed in breast cancer metastases, compared with primary tumour samples, supporting a role for PRODH in metastasis formation." (PMID 31819197, 2020). "Therefore, we suggest that proline accumulation induces PRODH/POX-dependent pro-survival pathways in PRODH/POX silenced MCF-7 human breast cancer cells." (PMID 29568391, 2018). "Thus, we tested whether PRODH expression was increased in transformed breast cancer cells during spheroidal growth." (PMID 28492237, 2017). "Our in vitro data suggest that Prodh may be a drug target against metastasis formation, which is supported by the fact that PRODH is significantly higher expressed in metastases compared to primary breast cancers in patients (P≤0.01, two-tailed unpaired Student's T-test with Welchs correction)." (PMID 28492237, 2017). "Here, our data suggest that PRODH decreases GPX4 expression and enhances ferroptosis in breast cancer cells." (PMID 39457440, 2024). "The importance of POX/PRODH as a pro-tumor agent was also highlighted in breast cancer, particularly in breast cancer metastases." (PMID 35454935, 2022). "The data provide evidence that the studied NSAIDs induce PRODH/POX-dependent and independent apoptosis in MCF7 breast cancer cells." (PMID 35409177, 2022). "Telmisartan, PPAR-γ ligand was found to inhibit collagen biosynthesis in breast cancer cells, supporting free proline for PRODH/POX-dependent functions." (PMID 34943229, 2021). "It seems that in estrogen receptor-positive breast cancer cells, prolidase supports proline for collagen biosynthesis, limiting its availability for PRODH/POX-dependent apoptosis." (PMID 34943229, 2021). "In ER positive, wild type breast cancer MCF-7 cells treated with TGZ, the expression of PRODH/POX was increased independently of the presence or absence of estradiol, while ROS production and expression of apoptosis markers were not affected." (PMID 34682765, 2021). "In MCF-7 breast cancer cells, Cx affected proline metabolism through upregulation of proline biosynthesis, PRODH/POX and PYCRs expressions, PEPD activity, and downregulation of collagen biosynthesis." (PMID 34577574, 2021). "The rational to use MCF-7 cells was also that in contrast to other breast cancer cells, e.g. MDA-MB-231, they evoke relatively high expression of PRODH/POX." (PMID 29568391, 2018).
breast cancer (continued). "As PRODH was previously shown to affect breast cancer cells’ growth in 3D but not 2D culture, we tested if the growth in 3D was also impaired by carrying out a colony formation assay in soft agar." (PMID 38255788, 2024). "We have found that NSAIDs induced PRODH/POX and PPARγ expressions (as demonstrated by Western Blot or immunofluorescence analysis) and cytotoxicity (as demonstrated by MTT, cytometric assay, and DNA biosynthesis assay) in breast cancer MCF7 cells." (PMID 35163433, 2022). "Breast cancer MCF7 and PRODH/POX CRISPR/Cas9 knockout MCF7 cells (MCF7POX-KO) were treated with 0.5 mM indomethacin and 0.375 mM diclofenac for 24 h to recognize the role of PRODH/POX in NSAID-dependent apoptosis." (PMID 35409177, 2022). "TGZ induces PRODH/POX expression in both wild type breast cancer cells independently of the presence or absence of estradiol." (PMID 34682765, 2021). "By using MDA-MB-231 breast cancer cells deprived of estrogen receptor β(ERβ) or cultured in medium without estradiol to establish the triple-negative breast cancer (TNBC) model, troglitazone treatment has been demonstrated to induce PRODH-mediated apoptosis through activating PPARγ in TNBC." (PMID 38023181, 2023). "In several mouse models of metastatic breast cancer, inhibition of PRODH could inhibit the formation of metastases without adverse effects on normal cells." (PMID 36998464, 2023). "The role of PRODH/POX in regulation of breast cancer cell apoptosis/autophagy is not known." (PMID 29568391, 2018). "Although the MET-dependent inhibition of ERK1/2 signaling in breast cancer cells is well established, the similar effect of MET on PRODH/POX knocked out cells is not known." (PMID 35733940, 2022). "The underlying mechanism involves activation of PRODH/POX (by PPAR-γ ligand, TGZ) that under availability of proline (substrate for PRODH/POX) and dependently on the ER status (absence of estradiol or ERβ) induces apoptosis in ER negative breast cancer cells." (PMID 34682765, 2021). "Relevant to inhibitor discovery, the noncovalent PRODH inhibitor S-(-)-tetrahydro-2-furoic acid (THFA) was shown to inhibit the spheroidal growth of breast cancer cells and impair the formation of lung metastases in mouse models of breast cancer." (PMID 39598797, 2024).